KRAS (KRas proto-oncogene, GTPase)
Diseases named in the same sentence as KRAS in open-access papers (continued):
Sharing a sentence is not in itself a finding about the gene and the disease.
cancer (continued). "KRAS mutation rates are higher in PDAC than any other cancer, so it is often assumed to be an exclusively KRAS-driven disease, but emerging data from large NGS-based studies suggest that 15–25% of cases harbor WT KRAS or display a low variant allele frequency (VAF) of the mutant form." (PMID 35008248, 2021). "In accordance with discovery of the G12C inhibitor, there have been recent successful attempts at developing a rudimentary KRas G12D inhibitor that showed efficacy in cell-based assays and may point toward an additional method of treatment for KRas-driven cancers in the future." (PMID 34680208, 2021). "However, given the spheroid-promoting activity that we observed in some KRAS mutant cancer cell lines, this compound could be problematic if these observations translated into the patient situation." (PMID 33672199, 2021). "We and others have shown that dampening KRAS signaling by targeting SHP2 may provide a tractable strategy for the treatment of cancers driven by the major (codon 12) oncogenic KRAS mutants, including non-small-cell lung cancer (NSCLC), gastroesophageal cancer, and PDAC17–22." (PMID 34725361, 2021). "Long‐term studies targeting KRAS mutations in cancer have not been successful." (PMID 34288405, 2021). "KRAS-mutant cancer cells could become adaptive to glutamine depletion through asparagine biosynthesis by ASNS; pronounced growth suppression was observed upon ASNS knockdown, indicating that ASNS might be a novel therapeutic target against tumors with mutated KRAS." (PMID 33922558, 2021). "These biallelic KRAS mutations tended to occur in non-immunogenic cancers." (PMID 34256801, 2021). "It should be considered that an enrichment of the KRAS GS in this present study was observed due to overlapping genes found with the GS EMT, which is a cellular program that reverts epithelial cells to mesenchymal cells and is often implicated in cancer, since it promotes metastasis and invasion." (PMID 33763387, 2021). "However, more studies are needed to determine whether there is a consistent change in methylation patterns in the subtypes of PDAC and whether oncogenic KRAS controls the epigenomic changes that are crucial for cancer phenotype." (PMID 34805167, 2021). "However, the emergence of covalent inhibitors to target KRAS has enabled the development of PROTACs capable of inducing endogenous KRASG12C degradation in cancer cells, such as LC-2 that couples the covalent KRASG12C inhibitor adagrasib to the von Hippel–Lindau (VHL) ligand." (PMID 35083149, 2021). "KRAS mutations are considered to occur during initiation or early event in colorectal carcinogenesis, but not in the malignant progression of CRC because it has been found in dysplastic lesions and adenomatous polyps, and such mutations alone are insufficient for the sustained growth of cancer." (PMID 33982211, 2021). "cfChIP targeting somatic cancer mutations is a promising new methodology for which the basis of liquid biopsies could help understand how expression of mutated oncogenic drivers such as EGFR, ALK, MET and KRAS contribute to carcinogenesis." (PMID 34453867, 2021). "While RAS is predominantly in its GDP-bound inactive state in normal quiescent cells, mutations in KRAS render it persistently GTP-bound and constitutively active, independent of extracellular stimuli, resulting in the activation of effector signaling pathways that drive cancer growth." (PMID 34680229, 2021). "Thus, targeting the MYC oncogene could be a potential therapeutic strategy for MYC-dependent cancers such as KRAS-mutant CRC." (PMID 34944853, 2021). "Moreover, KRAS-driven cancer cells become “addicted” to glutamine and also require it for growth." (PMID 33742081, 2021). "However, emerging data suggest that KRAS zygosity may profoundly affect cancers’ phenotypes and responses to targeted compounds." (PMID 34573384, 2021).
cancer (continued). "We used publically available data from the cancer cell line encyclopaedia (CCLE) database to search for mutations in EGFR, ERBB2, ERBB3, ERBB4, KRAS and BRAF that might predispose to a different response to anti-HER2 therapies or PI3K or MAPK pathway inhibition." (PMID 33933113, 2021). "Thus, targeting KRAS and its pathway in cancers of the blood has been challenging." (PMID 33801965, 2021). "Interestingly, BRD9 is negatively correlated with PIK3CA; its correlation with KRAS is non-uniform, though it has been shown that BRD9 may mediate a PI3KCA-KRAS mutant oncogenic cancer phenotype." (PMID 34944438, 2021). "Moreover, the broad spectrum of tumors responding to inhaled topotecan may offer additional therapies following progression of EGFR or KRAS mutant cancers." (PMID 33860729, 2021). "Despite being in the dose escalation phase, CCT3833 achieved a progression-free survival (PFS) of >10 months, and we provide comprehensive analysis of the mechanism of action of CCT3833 in KRAS-mutant cancers to reveal how this patient and others could benefit from this agent." (PMID 33130216, 2021). "Thus, inhibitors of DDR-promoting kinases may preferentially target the growth of KRAS mutant cancer cells by allowing G2/M progression to proceed in the presence of unrepaired DNA damage." (PMID 34852220, 2021). "KRAS oncogenic mutations lead to the continued activation of downstream molecules, and the KRAS/mitogen-activated protein kinase (MAPK) signaling pathway is strongly associated with the development of PC, both of which enhance the malignant potential of this cancer." (PMID 34512755, 2021). "However, tipifarnib has been evaluated in HRAS mutated cancers only, since KRAS is prenylated by geranylgeranyl transferase and does not need farnesylation for membrane localization." (PMID 33777798, 2021). "In summary, compared with MAPK pathway inhibitors, monotherapy or combination therapy with PI3K pathway inhibitors has limited benefits for patients with KRAS-mutated cancers, although such PI3K inhibitors may reverse resistance to KRAS-G12C inhibitors (discussed later)." (PMID 34607583, 2021). "Thus, our data unveil the upregulation of the selected AATs (SLC1A5/ASCT2, SLC7A5/LAT1, and SLC38A2/SNAT2) as a prognostic marker of poor survival of patients with CRC, useful for cancer patient stratification, in particular with regard to the KRAS mutant subtype of patients." (PMID 34003553, 2021). "Consequently, the combination of this new drug with a MEK inhibitor could be a good option for future research on KRAS-driven cancers." (PMID 35083149, 2021). "In the GSEA results, enriched pathways, such as the EMT, hypoxia, KRAS signaling, angiogenesis, Notch and Hedgehog signaling pathways, were significantly positively associated with ISM1, and most of these pathways are vital to cell proliferation, migration and resistance in cancer, including CRC." (PMID 34350177, 2021). "Thus, the KRAS mutation does not likely solely account for differences in cancer cell fate upon treatment with RRSP." (PMID 34504197, 2021). "Moreover, AGO2-mutated KRAS interaction holds crucial importance in pancreatic ductal adenocarcinoma progression, where AGO2 expression is required for overcoming oncogene-induced senescence and cancer development." (PMID 33668654, 2021). "Interestingly, Glutamine depravation in KRAS mutant cancer cells leads to apoptosis." (PMID 34107900, 2021). "The stress‐activated kinases c‐Jun N‐terminal kinase (JNK) and the mitogen‐activated protein kinase (MAPK) p38 play a key role in response to stress insults, and we therefore explored whether elevated ROS upon FGFR/PLK1 inhibition can activate JNK and p38 in KRAS‐mutant cancer cells." (PMID 34369083, 2021).
cancer (continued). "Thus, for each cancer, the allelic frequency of KRAS was not caused primarily by distinct compositions of mutational processes in individual tumors." (PMID 33753749, 2021). "Indeed, cancer cell lines driven by either HRAS or KRAS have been shown to differentially regulate autophagy, indicating that the level of RAS effector pathway activation and signaling “fine-tuning” may have an important influence on the autophagic machinery." (PMID 34298710, 2021). "Furthermore, modulating metabolism in KRAS mutant cancers may be a potential opportunity for the development of novel detection and treatment strategies in PC." (PMID 33692690, 2021). "In addition, inhibiting SOS1 increases the sensitivity of KRAS mutant cancers to MEK inhibition." (PMID 33801965, 2021). "Thus far, high-throughput resequencing efforts worldwide aimed at identifying unknown somatic mutations in human cancer have already revealed that yet uncharacterized mutations in KRAS, NRAS, BRAF, PIK3CA, PTEN and other cancer genes are highly prevalent." (PMID 32620824, 2020). "However, cancer-related mutant KRAS cell-free DNA analysis revealed that only 2/32 (6%) did not have KRAS mutation detected." (PMID 32063605, 2020). "Considering that some mutations such as KRAS G12D and BRAF V600E are selectively enriched during cancer development, which could skew our estimation of mutation tendency, we excluded mutational events that occur in more than five cancer samples (see “Methods” for further discussion)." (PMID 32704382, 2020). "However, some types of KRAS mutation could impair the GAP binding to KRAS and lead to a continuous GTP-bound KRAS status to promote the proliferation related pathways and cancer development." (PMID 32547859, 2020). "However, detailed mechanisms of the actions of PLK1 inhibitors on KRAS mutant cancers are largely unknown." (PMID 32486290, 2020). "Ultimately, a better understanding of the DNA methylation events associated with oncogenic KRAS expression could enhance therapeutic approaches for KRAS-driven cancers and provide a platform for understanding the intrinsic heterogeneous nature of these cancers." (PMID 32576853, 2020). "The results indicate that PTPN2 may be a novel therapeutic target for KRAS-driven cancers." (PMID 33122197, 2020). "Although it is early to evaluate the benefits of the mentioned approaches, the exploration of these opportunities could result in overcoming KRAS-resistance mechanisms and the forthcoming results are expected to bring new therapeutic benefit for patients with KRAS-mutant cancer." (PMID 33116132, 2020). "Thus, elevated cyclin A2 in KRAS mutant cancers may reflect anadaptation mechanism from this cell cycle stress at the S phase." (PMID 32486290, 2020). "Our data suggest that PTPN2 could serve as a potential therapeutic target for KRAS-driven cancer." (PMID 33122197, 2020). "KRAS mutated models in direct comparison with all other models used in this study seemed to be more convenient for general research purposes, presenting a robustly high percentage of malignant tumors but a low rate of benign or non-neoplastic lesions." (PMID 32823526, 2020). "Indeed, the complexities of KRAS genetics in cancer are difficult to clearly explain." (PMID 32404198, 2020). "This suggests that while many DNA methylation changes could be stochastic in nature and simply “passenger” events, or a consequence of their cell state and cell lineage, KRAS is likely still able to influence key changes to the epigenome that are ultimately crucial for the cancer phenotype." (PMID 32576853, 2020).
cancer (continued). "In addition to regulating AR, GSEA and additional gene ontology analysis of genes differentially expressed following ERβ activation revealed an enrichment of genes involved in cancer-related processes, including apoptosis, response to hypoxia, KRAS signaling, and key metabolic pathways." (PMID 32413024, 2020). "Accordingly, we speculate that inhibition of ASCT2 function is more effective for KRAS‐mutated cancer than for wild‐type KRAS cancer regardless of the ASCT2 expression level." (PMID 31709772, 2020). "Recent studies suggest that the effects of KRAS on redox homoeostasis are required for maintaining the cancer phenotype and may thus represent attractive therapeutic targets for KRAS-driven cancers, which still represent a clinical challenge due to the lack of effective therapies." (PMID 31819197, 2020). "Moreover, mSLED allows us to answer questions in cancer mechanobiology on faster timescales, and as we report here, KRas oncogene activation disrupts the ability of breast epithelial cells to respond to acute extracellular mechanical cues with rapid calcium signaling." (PMID 33020304, 2020). "By conducting four μs MD simulations, we confirm that high cholesterol in the PM helps KRas-4B mutant stays in its constitutively active state, which suggests that high cholesterol intake can increase mortality and may promote cancer progression for cancer patients." (PMID 33266473, 2020). "However, for an ideal KRAS G12D cancer vaccine, activated Th1 immune responses are crucial." (PMID 32903495, 2020). "However, little is known about whether ICMT function sustains cancer cell stemness properties in KRAS-driven cancers." (PMID 32561852, 2020). "Importantly, this resistance to SHP2 inhibition may also occur in KRAS or BRAF mutant cancers wherein FGFRs are feedback activated due to MAPK inhibition, as evidenced by the observations in SW1736 cells." (PMID 32076487, 2020). "Therefore, the present results imply that 12p gains may be indispensable for the development of ECs because 12p includes various genes associated with cancer (e.g., DPPA3, GDF3, KRAS, or CCND2)." (PMID 32999426, 2020). "Interestingly, accumulating literature has demonstrated that oxidative phosphorylation (OXPHOS) is upregulated in some glycolytic cancers, including PDAC, which might be driven by the oncogene KRAS and the loss of LKB1." (PMID 33256814, 2020). "Whilst these studies highlighted KRAS mutations as contraindication for TRAIL-R agonistic treatments, the function and reasons for high endogenous expression of TRAIL and TRAIL-Rs observed in these cancers remained unknown." (PMID 32194994, 2020). "However, the background of mutant KRAS may be contributing to these findings as mutant HRAS or KRAS cancers are sensitive to enhanced proteotoxic stress and ER stress." (PMID 30860482, 2019). "As with all current targeted cancer therapeutics, MEKi efficacy is limited by innate and acquired resistance and we have contributed to the understanding of both modes of MEKi resistance in colorectal cancer (CRC) cells, where BRAF and KRAS mutations are common oncogenic drivers." (PMID 35582726, 2019).
cancer (continued). "Importantly, KRAS-mutant cancer cells differing in EMT status vary in their responses to MEK inhibitors, as EMT rewires the expression of receptor tyrosine kinases (RTKs), a consequence of differential feedback activation of the MAPK pathway following MEK inhibition." (PMID 31612108, 2019). "Thus inhomogeneous distribution of KRAS mutation in cancer tissue seems not to influence the result of screening of EBC–DNA for the presence of KRAS mutation." (PMID 30368666, 2019). "In addition, the identification of synthetic lethal interactors of KRAS may provide useful targets for therapeutic intervention in KRAS-driven cancers." (PMID 31847096, 2019). "Since intracellular KRAS activity is difficult to disrupt, and activated KRAS has been demonstrated to trigger death pathways, changing the nature of KRAS signaling from pro-survival to pro-death by directly targeting KRAS in cancer cells may represent an entirely new strategy for cancer therapy." (PMID 30971271, 2019). "Our results describe that IQGAP1 could regulate MEK localization in KRAS mutant cancer cells." (PMID 30833665, 2019). "Similarly, in mutant KRAS cancers, autophagy induction occurred under starvation." (PMID 31671556, 2019). "Mutations of KRAS and HRAS in cancer affect the efficacy of chemotherapy; changes in TRP channel expression could overcome drug resistance and increase the sensitivity of cancer cells to chemotherapy." (PMID 31801263, 2019). "Therefore, the S-phase checkpoint is an exciting opportunity for therapeutic intervention in KRas-driven cancers because the S phase of the cell cycle is the most carefully modulated phase of the cell cycle, where the cell is replicating its genome and separating the chromosomes." (PMID 31489935, 2019). "Compounds that covalently attach KRAS G12C, antagonists of RAS-membrane association and downstream effector signaling and strategies to target downstream signaling of KRAS by inhibition of PI3K/Akt or Raf/MEK/ERK have shown promise in preclinical models of RAS-induced cancer." (PMID 30323311, 2019). "The top 15 SGA-FIs connected with CSMD3 and ZFHX4 also form densely connected networks that include well-known cancer drivers, such as KRAS, GATA3, KEAP1, ERBB2 and STK11, suggesting that alteration of CSMD3 and ZFHX4 may perturb some of the same signaling pathways as do these known drivers." (PMID 31276486, 2019). "Furthermore, treatment with 100 μM DMF for 24 h decreased HO-1, total NRF2 and total DJ-1 levels in the KRAS mutated P4; but not in the KRAS wild type P1 primary cancer cell lines." (PMID 29507676, 2018). "Finally, this mechanism could also be at the base of the modest successes of mTOR inhibitors, especially in KRAS driven cancer." (PMID 31225458, 2018). "Moreover, the Panitumumab-resistant cancer cells (KRAS-mutant) will survive." (PMID 35847834, 2018). "Finally, we provide proof-of-concept data suggesting that KRAS/IKKα addiction may occur in human cancers and may be targeted by combined KRAS/IKKα inhibition." (PMID 29445180, 2018). "Based on these 19 drug-variant combinations, 4 out of 6 sensitive mutations in DEPO (KRAS G12V, BRAF V600E, NRAS Q61K, and KRAS G12D) were significantly associated with sensitivity to at least one of their paired drugs in both the cancer-type-specific and non-specific settings." (PMID 30053901, 2018). "Therefore, deep sequencing dozens to hundreds of cancer-related genes have to be carefully evaluated to determine if the benefits outweigh the disadvantages, especially for PDAC, where at least one of a few KRAS variants are observed in most cases." (PMID 30072705, 2018). "All of these cancer models maintained the original KRAS-G12D mutation (data not shown)." (PMID 29599906, 2018).